PLOD2 (procollagen-lysine,2-oxoglutarate 5-dioxygenase 2)
Diseases named in the same sentence as PLOD2 in open-access papers (continued):
Sharing a sentence is not in itself a finding about the gene and the disease.
lung carcinoma (19 papers, 2017 to 2025). "High PLOD2 expression is associated with poor outcomes in patients with liver, breast, and lung cancer." (PMID 32958051, 2020). "Additional research has reported that paracrine signals from cancer-associated fibroblasts enhance PLOD2 expression in lung cancer." (PMID 30563531, 2018). "The data suggested that PLOD2 was associated with poor prognosis of lung cancer patients, especially in lung adenocarcinoma patients but not in lung squamous cell carcinoma patients." (PMID 29072684, 2017). "In addition, paracrine signals from cancer-associated fibroblasts (CAFs) can also upregulate PLOD2 expression in lung cancer." (PMID 30563531, 2018). "We found that P4HA2 and PLOD2 were up-regulated in both breast and lung cancer cell lines, T47D and H1299, respectively." (PMID 36826019, 2023). "RASSF1C up-regulation of P4HA2 and PLOD2 expression in both breast and lung cancer cells was confirmed by RT-PCR analysis." (PMID 36826019, 2023). "P4HA2 and PLOD2 expression was confirmed in breast and lung cancer cells overexpressing RASSF1C by RT-PCR." (PMID 36826019, 2023). "We have assessed P4HA2 and PLOD2 expression in vivo using lung tissue derived from an orthotopic metastasis model using lung cancer cell lines A549 and H1299." (PMID 36826019, 2023). "Recent studies found a significant correlation between PLOD2 and infiltrating immune cells including neutrophils in cervical, hepatocellular and lung cancer." (PMID 35682709, 2022). "In lung cancer cell lines, ectopic PLOD2 expression rescued the migration and metastasis defects resulting from HIF-1α silencing, and the defects were again reinstated by concomitant inhibition of PLOD2 activity." (PMID 31446433, 2019). "In lung cancer tissue, PLOD2 has been shown to hydroxylate telopeptidyl lysine residues on collagen, which indirectly reduces the levels of lysine aldehyde–derived collagen cross-links." (PMID 31446433, 2019). "In lung cancer, PLOD2 expression in CAFs resulted in the collagen contractile network formation and promoted tumor migration along the collagen network, while depletion of PLOD2 expression in CAFs diminished collagen network formation." (PMID 31170987, 2019). "Breast and lung cancers with high PLOD2 expression display enhanced rates of migration and metastasis." (PMID 30563531, 2018). "In this study, we analyzed human lung tumor samples and found that PLOD2 was upregulated in lung cancer." (PMID 29072684, 2017). "Studies have shown that FOXA1 could regulate the expression of cell marker PLOD2 by binding to promoters, thereby affecting the occurrence and development of lung cancer." (PMID 34986601, 2022). "Studies showed that FOXA1 could regulate the expression of cell marker PLOD2 by binding to its promoters, thereby affecting the occurrence and development of lung cancer; (ii) T Marker: markers, which are regulated by TFs." (PMID 34986601, 2022). "PLOD2 hydroxylates telopeptidyl lysine residues on collagen, subsequently increasing the level of hydroxylysine aldehyde–derived collagen cross-links (HLCCs) and lowering levels of lysine aldehyde–derived cross-links in lung cancer tissue." (PMID 30003082, 2018). "However, a recent study shows that PLOD2 protein can be secreted by lung cancer cells and induce collagen remodeling." (PMID 30003082, 2018). "Next, we needed to study the role of PLOD2 in lung cancer progression." (PMID 29072684, 2017). "Similarly, inhibition of PLOD2 by Minoxidil reduced tumor migration in lung carcinoma and might prevent metastasis in this type of cancer." (PMID 35682709, 2022). "Also in lung cancer cells, elevated PLOD2 expression promotes collagen cross-links, activates the phosphoinositide 3-kinase pathway, and may promote proliferation, invasion, and migration." (PMID 31446433, 2019). "Consistent with RT-PCR analysis, lung cancer cells overexpressing RASSF1C had increased P4HA2, PLOD2, and collagen I protein levels." (PMID 36826019, 2023).
lung carcinoma (continued). "We also found that silencing of RASSF1C in lung cancer cells resulted in the down-regulation of P4HA2 and PLOD2." (PMID 36826019, 2023). "We were able to identify the P4HA2 and PLOD2 genes as RASSF1C target genes in both breast and lung cancer cells." (PMID 36826019, 2023). "We found overexpressing PIWIL1, like RASSF1C, promotes lung cancer cell migration/invasion and that PIWIL1 overexpression resulted in increased expression of P4HA2, PLOD2, and collagen I protein levels suggesting that PIWIL1 could play a role TME remodeling." (PMID 36826019, 2023). "In this regard, we report that RASSF1C and PIWIL1 may promote lung cancer cell metastasis through modulation of tumor microenvironment/ECM through regulation of Collagen I, P4HA2, and PLOD2 gene expression." (PMID 36826019, 2023). "Thus, our findings suggest that the RASSF1C-PIWIL1 pathway could potentially promote lung cancer microenvironment/ECM remodeling to induce lung cancer cell stemness and metastasis, in part, via modulation of P4HA2 and PLOD2 expression." (PMID 36826019, 2023). "In support of this idea, we found that overexpression of PIWIL1 promotes lung cancer cell migration/invasion, which is consistent with published reports; and cells overexpressing PIWIL1 display increased protein levels of P4HA2, PLOD2, and collagen I to some extent." (PMID 36826019, 2023). "We do not know if the inhibition of lung cancer cell migration/invasion by piR-35127 and piR-46545 may involve modulation of P4HA2 or PLOD2 expression." (PMID 36826019, 2023).
cervical carcinoma (18 papers, 2017 to 2025). A carcinoma arising from either the exocervical squamous epithelium or the endocervical glandular epithelium. "Specifically, PLOD2 is up-regulated in several types of cancer, including cervical cancer, and is associated with cancer metastasis." (PMID 28507454, 2017). "The validation of PLOD2 as a prognostic gene highlights its therapeutic potential, underscoring the critical need for integrating immunotherapy and targeted treatment strategies to enhance diagnostic and therapeutic approaches in cervical cancer." (PMID 39840054, 2024). "PLOD2 is implicated in cervical cancer and renal cell carcinoma." (PMID 34116656, 2021). "Thus, in this research, we aimed to investigate the role of PLOD2 in the motility of cervical cancer cells and to show the molecular mechanism underlying this effect." (PMID 28507454, 2017). "Moreover, a database analysis showed that PLOD2 expression is associated with human cervical cancer progression." (PMID 28507454, 2017). "PLOD2 is an effective prognostic marker, which is related to the immune infiltration of cervical cancer." (PMID 38656879, 2024). "We conducted in vitro research to shed further light on the prognostic gene PLOD2’s function in cervical cancer." (PMID 39840054, 2024). "In vitro experiments validated that the prognostic gene PLOD2 significantly enhances proliferation, migration, and invasion of cervical cancer cells." (PMID 39840054, 2024). "PLOD2 gene silencing dramatically decreased the quantity and size of colonies produced by cervical cancer cell lines, as shown by plate cloning tests." (PMID 39840054, 2024). "Taken together, overexpression of hypoxia-pathway-related genes, such as NDRG1, HK2, and PLOD2, is induced by the OSM-STAT3 axis, and higher expression levels of these genes are significantly associated with poor prognosis in cervical cancer patients." (PMID 36551576, 2022). "Third, we herein investigated the effect of PLOD2 on two types of cervical cancer cells, and the overall effects of PLOD2 were more evident in the squamous cell carcinoma cell line (SiHa) than the adenocarcinoma cell line (HeLa)." (PMID 28507454, 2017). "The results of this study do support that PLOD2 regulates the migratory, invasive and adhesive capacities of cervical cancer cells." (PMID 28507454, 2017). "Hypoxia has been shown to induce the expression of PLOD2 in various cell types, including cervical cancer cells." (PMID 28507454, 2017). "Differences in PLOD2 expression among patients with cervical cancer were identified by referring to public databases, including Oncomine and TCGA." (PMID 28507454, 2017). "Comparisons between different types of samples among studies subsequently suggested that PLOD2 is up-regulated in squamous cell carcinomas relative to cells of the normal cervix and high-grade squamous intra-epithelial lesion and could be associated with the invasiveness of cervical carcinoma cells." (PMID 28507454, 2017). "Overall, our results indicated that hypoxia- and TGF-β1-induced PLOD2 expression promotes the migratory, invasive and adhesive capacities of cervical cancer cells by participating in TGF-β1 induced EMT and the formation of focal adhesions." (PMID 28507454, 2017). "Some other studies have shown DSG2, PLOD2, ANLN, AURKA, and AR genes might be key genes associated with cervical cancer progression." (PMID 41266827, 2025). "Notably, the knockdown of PLOD2 markedly reduced migration, invasion, and proliferation in SiHa and HeLa cells, underscoring its potential role in cervical cancer progression." (PMID 39840054, 2024). "Moreover, experimental validation highlighted the potential of PLOD2 as a therapeutic target in cervical cancer." (PMID 39840054, 2024). "In cervical cancer, PLOD2 is expressed in response to TGF-β and hypoxia." (PMID 35625561, 2022).
cervical carcinoma (continued). "This means that PLOD2 expression may promote the migratory, invasive, and adhesive capacities of cervical cancer cells by affecting ECM; this could be further researched through in vitro and in vivo experimental studies." (PMID 34258263, 2021). "The results in this study revealed the critical role of PLOD2 in CESC, and it may serve as a potent prognostic marker and be associated with immune infiltration in cervical cancer." (PMID 34258263, 2021). "In cervical cancer, PLOD2 influenced migration and invasion of cervical cancer cells." (PMID 34944486, 2021). "Further research has suggested that PLOD2 is involved in TGF-β-induced EMT in cervical cancer." (PMID 30563531, 2018). "Collectively, these data indicate that PLOD2 warrants further exploration in cervical cancer and might be a potential biomarker that can predict metastasis and serve as a valuable therapeutic target for the prevention of metastasis in cervical cancer." (PMID 28507454, 2017). "siRNA was used to knockdown PLOD2 in the cervical cancer cell lines HeLa and SiHa." (PMID 28507454, 2017). "Therefore, we focused on MMP-2 and MMP-9 when investigating the molecular mechanism by which PLOD2 reduces the migration and invasion of cervical cancer cells in hypoxic conditions." (PMID 28507454, 2017). "Therefore, further studies are required to establish the role of PLOD2 in different histological types of cervical cancer." (PMID 28507454, 2017). "Specifically, PLOD2 mRNA was up-regulated in 20% of 307 patients with cervical cancer." (PMID 28507454, 2017). "According to the research about PLOD2 in fibroblasts and CAFs, we propose that it probably participate in the communication of tumour cells with fibroblasts in the tumour stroma, which also deserves further exploring in cervical cancer." (PMID 28507454, 2017). "Notably, PLOD2 is located between 3q21 and 3q26, a chromosomal region previously reported to be amplified in cervical cancer." (PMID 28507454, 2017). "This evidence indicated that PLOD2 might play a crucial role in cervical cancer progression." (PMID 32258155, 2020). "In addition to the previously reported mechanism mediated by PLOD2 in other cancer types, we elucidated its influence on the typical malignant behaviour of cervical cancer cells, which affects several mechanisms that regulate cancer metastasis, such as cell adhesion, migration and invasion." (PMID 28507454, 2017). "In vitro experiments validated the impact of PLOD2, a key gene within the NCRS, on the biological activity of cervical cancer cells." (PMID 39840054, 2024). "Subjecting cervical cancer cell lines to hypoxia increased the levels of HIF-1α and PLOD2, and the migration and invasion of cells mediated by PLOD2 were dependent on HIF-1α." (PMID 35625561, 2022). "However, the prognostic value of PLOD2 in cervical cancer (CESC) remains unclear." (PMID 34258263, 2021). "However, the role of PLOD2 in cervical cancer remains unknown." (PMID 32258155, 2020). "In cervical carcinoma, hypoxia- and TGF-β-induced PLOD2 expression increases the proliferative, adhesive, and invasive capabilities of cells by promoting the epithelial–mesenchymal transition and formation of focal adhesions." (PMID 31446433, 2019). "Thus, PLOD2 may have therapeutic value in the prevention of cervical cancer metastasis." (PMID 28507454, 2017). "Thus, we hypothesized that PLOD2 controls the migration and invasion of cervical cancer cells." (PMID 28507454, 2017). "In particular, the NDRG1, HK2, PLOD2, EGLN3, and NPC1 genes showed a higher expression in tumors than in normal tissues, and cervical cancer patients overexpressing these genes had a poor prognosis compared with those who showed low expression levels of these genes." (PMID 36551576, 2022).
cervical carcinoma (continued). "Overall, our findings suggest that the hypoxia-related genes, including NDRG1, HK2, and PLOD2, can be controlled by inhibiting STAT3, and this strategy is a novel therapeutic option that may effectively reduce the progression of cervical cancer." (PMID 36551576, 2022). "Then, we confirmed by Western blot that the expression of PLOD2 in the cervical cancer cell line was higher than that in normal cervical cells." (PMID 34258263, 2021). "First of all, the PLOD2-mediated remodelling of the ECM has not been investigated in cervical cancer, which is a complex progress involving multiple cellular components and numerous cell biological process related to tumour progression." (PMID 28507454, 2017). "However, we did not thoroughly explore the function of PLOD2 in cervical cancer in our study." (PMID 28507454, 2017).
gastric cancer (13 papers, 2020 to 2025). A primary or metastatic malignant neoplasm involving the stomach. "The authors showed that PLOD2 promotes cell invasiveness and migration in gastric cancer under hypoxia and leads to peritoneal dissemination of gastric cancer." (PMID 40906383, 2025). "PLOD2 expression has also been shown to be a prognostic indicator in various cancers, including gastric cancer and osteosarcoma." (PMID 40906383, 2025). "Next, we analyzed the relationship between PLOD2 expression and infiltrating immune cells in gastric cancer based on the xCELL algorithm." (PMID 35586565, 2022). "In conclusion, we have found that PLOD2 can serve as a valuable prognostic biomarker for some tumors, especially gastric cancer." (PMID 35586565, 2022). "Immunohistochemical results also showed that the PLOD2 expression in gastric cancer was significantly higher than normal tissues." (PMID 35586565, 2022). "For gastric cancer, the median overall survival time was significantly higher in the PLOD2 low expression group [HR 0.616 (95%CI 0.442–0.858), p = 0.004]." (PMID 35586565, 2022). "We further analyzed the relationship between PLOD2 gene expression and prognosis in gastric cancer patients in detail." (PMID 35586565, 2022). "To that end, we will elucidate the expression of PLOD2 in 33 different malignant tumors in the following aspects and focus on gastric cancer." (PMID 35586565, 2022). "Lastly, twenty pairs of gastric cancer and adjacent immunohistochemistry showed that PLOD2 was significantly overexpressed in gastric cancer (p < 0.001)." (PMID 35586565, 2022). "PLOD2 regulated by HIF-1 is a potential regulator of peritoneal dissemination of gastric cancer." (PMID 40906383, 2025). "The PLOD family includes PLOD1, PLOD2, and PLOD3, all of which may be linked to various cancers, including gastric cancer, sarcoma, and liver cancer." (PMID 36820030, 2023). "In order to investigate the research status of PLOD2 and gastric cancer, we conducted a search on the PubMed using the following search strategy: [“stomach neoplasms” (Title/Abstract) OR “stomach neoplasms” (MeSH Terms) OR “gastric adenocarcinoma” (Title/Abstract)] AND [“PLOD2” (Title/Abstract)]." (PMID 35586565, 2022). "Downregulation of PLOD2 facilitated the sensitivity of gastric cancer to 5-FU in vivo." (PMID 35586565, 2022). "Another study on PLOD2 and 5-FU resistance in gastric cancer showed that PLOD2 could enhance 5-FU resistance by regulating BCRP and inhibit cell apoptosis by affecting the expression of Bax and Bcl2." (PMID 35586565, 2022). "PLOD2 only showed increased expression in gastric cancer in Wang dataset." (PMID 31892979, 2020). "The aberrant function of PLOD2 might have a role in ovarian cancer and gastric cancer progression." (PMID 36901940, 2023). "For example, PLOD2 can increase the invasiveness and migration of gastric cancer (GC) cells and promote their resistance to 5-fluorouracil by upregulating BCRP and inhibiting apoptosis." (PMID 35265665, 2021). "Existing literature has reported a certain correlation between PLOD2 and HIF1A in gastric cancer and endometrial carcinoma." (PMID 38008826, 2023). "For example, a study found that a set of enzymes PLOD1, PLOD2 and PLOD3 involved in the hydroxylation of lysine and stabilization of collagen by crosslinks, which up-regulated expression in gastric cancer patients." (PMID 35111402, 2022). "Overexpression of PLOD2 upregulated the expression of BCRP protein and inhibited apoptosis by decreasing BAX and increasing the level of Bcl2, enhancing the resistance of gastric cancer cells to 5-FU." (PMID 32284742, 2020). "Knockdown of PLOD2 downregulated the expression of BCRP protein, while increasing BAX and decreasing the level of BCL2 promoted apoptosis, reducing the resistance of gastric cancer to 5-FU." (PMID 32284742, 2020).
gastric cancer (continued). "Their results showed that PLOD2 knockdown in BGC823 cells significantly reduced the IC50 value of 5-FU, which contributed to the reduction of migration and invasion and promoted apoptosis of gastric cancer cells." (PMID 35586565, 2022).
renal cell carcinoma (13 papers, 2018 to 2024). "In this study, we detected a high level of m6A methylation of the PLOD2 3′-untranslated regions (3′UTR) in renal cell carcinoma (RCC)." (PMID 34179084, 2021). "Our previous studies showed that aberrant expression of PLOD2 was detected in BC and renal cell carcinoma tissues, and its overexpression enhanced cancer cell malignant transformation." (PMID 31199049, 2019). "Interestingly, the downregulation of LH2/PLOD2 isoform in renal cell carcinoma via tumor suppressing miRNA significantly inhibited cell migration and invasion, confirming the importance of LH in tumor progression." (PMID 36090047, 2022). "In agreement with the observations on PLOD2, also PLOD3 knockdown suppressed the malignant phenotype in renal cell carcinoma." (PMID 36090047, 2022).